GLI1 (GLI family zinc finger 1)
Diseases named in the same sentence as GLI1 in open-access papers (continued):
Sharing a sentence is not in itself a finding about the gene and the disease.
melanoma (continued). "Western blot analysis showed that both 1 and 2 reduced the expression of endogenous GLI1 protein in a dose-dependent manner in all three melanoma cell lines." (PMID 29396391, 2018). "A previous study reported that this pathway regulates the nuclear localization and transcriptional activity of GLI1 in melanoma cells." (PMID 30558232, 2018). "Here we show that 1 inhibits GLI1 expression and reduces melanoma cell growth in vitro and in vivo, by inducing DNA damage and G2/M cell cycle arrest." (PMID 29396391, 2018). "For instance, RAS-RAF-MEK-ERK and PI3K/AKT signaling have been shown to stimulate GLI1 activity in normal murine fibroblasts and melanoma cells." (PMID 30558232, 2018). "The WIP phosphatase has been shown to increase GLI1 function in melanoma by promoting GLI1 nuclear localization, protein stability and transcriptional activity." (PMID 30158435, 2018). "In consistent with the results from mouse model, the Gli-1 expression also correlates with tumor progression and metastasis in human melanomas." (PMID 28212537, 2017). "We find that itraconazole increases Gli-3, Axin-1 expression but decreases Gli-1, Gli-2, Axin-1, β-catenin, Wnt3A and Cyclin D1 expression in both melanoma cell lines when compared with untreated cells." (PMID 28212537, 2017). "For instance, oncogenic H- or N-Ras increase GLI1 function in melanoma cells and HH-GLI signalling is required for N-Ras-induced mouse melanoma growth (Ref." (PMID 25660620, 2015). "A recent global genomic screening of 100 melanomas revealed few missense mutations in the core genes of the HH pathway (PTCH1, SMO, SUFU, GLI1, GLI2 and GLI3) (Ref." (PMID 25660620, 2015). "Human melanoma stem cells with increased aldehyde dehydrogenase 1 (ALDH1) activity showed greater expression of GLI1." (PMID 26633513, 2015). "The evidence we provide represents a strong rationale to translate to a clinical setting the combinatorial strategy we have shown to be effective in counteracting the BRAF-I Gli1/PDGFRα-mediated resistance of melanoma cells both in vitro and in vivo." (PMID 24732172, 2014). "Pharmacologic inhibition of BRAFV600E in human melanoma cell lines resulted in decreased expression of GLI1 thus demonstrating interaction of SHH-GLI and MAPK pathways." (PMID 23935925, 2013). "Recently, several reports have shown that the HH-GLI signaling pathway plays an important role in RAS-induced tumorigenesis (among them melanoma) and that MAPK signaling pathway regulates the expression of GLI1 expression." (PMID 23935925, 2013). "In this study we show that NVP-LDE225 as well as the natural compound cyclopamine inhibit transcription of GLI1 in human melanoma cell lines." (PMID 23935925, 2013). "We demonstrate that both standard SHH-GLI inhibitor cyclopamine and the novel more specific inhibitor of smoothened NVP-LDE225 reduce the GLI1 promoter activity, induce G1 cell cycle arrest, and induce apoptosis in human melanoma cell lines." (PMID 23935925, 2013). "We performed quantitative RT-PCR to analyze the expression of the GLI1 as a surrogate marker of Hedgehog signaling pathway activity in human melanoma cell lines." (PMID 23935925, 2013). "This experiment suggests that increased Shh activation is partially responsible for the progression of malignant melanoma via Gli1 and OPN and that targeting of this pathway presents a promising therapeutic option." (PMID 24281103, 2010). "Therefore, additional immunohistochemical studies such as SOX10, Melan A, and HMB45 can be performed to distinguish melanoma from GLI1-rearranged enteric tumors." (PMID 39851545, 2025). "Additionally, we have recently reported that ERK5 is required for the HH/GLI-dependent melanoma cell proliferation and that GLI1, the major downstream effector of the HH/GLI signaling, positively regulates ERK5 expression." (PMID 39998753, 2025).
melanoma (continued). "Furthermore, targeting the transcription factors GLI1/GLI2 (nuclear effectors of the Hh pathway) was able to reverse the treatment resistance of melanoma cells refractory to BRAF inhibitors and even prevent the acquisition of resistance to chemotherapy." (PMID 40806546, 2025). "Melanoma cell-intrinsic activation of GLI1 promotes changes in the infiltration of immune cells, leading to accumulation of immunosuppressive PMN-MDSCs and regulatory T cells, and to decreased infiltration of dendric cells (DCs), CD8 + and CD4 + T cells in the TME." (PMID 39090759, 2024). "In this study we unveil a novel immunoregulatory role of GLI1 in the melanoma TME." (PMID 39090759, 2024). "Altogether these factors reinforce the immunosuppressive behavior of GLI1 in melanoma TME." (PMID 39090759, 2024). "Notably, PMN-MDSCs pre-conditioned with media from melanoma cells overexpressing GLI1 induced T cell death more efficiently than those pre-conditioned with control media." (PMID 39090759, 2024). "Finally, silencing of GLI1 in patient-derived melanoma cells promotes the activation of human monocyte-derived dendritic cells (moDCs), increasing cytoskeleton remodeling and invasion ability." (PMID 39090759, 2024). "However, the role of the downstream GLI1 transcription factor in melanoma TME remains largely unexplored." (PMID 39090759, 2024). "In addition, we show that ectopic expression of GLI1 in melanoma cells enables PMN-MDSC expansion and recruitment, and increases their ability to inhibit T cells." (PMID 39090759, 2024). "More recently, a pharmacophore-based virtual screening approach identified quinolines and oxazino-quinoline derivatives as small molecule GLI1 inhibitors characterized by submicromolar antiproliferative activity toward human melanoma and medulloblastoma cell lines." (PMID 36674836, 2023). "In support for a cause-effect relationship between GLI inhibition and the reduction in USP48 and iASSP mRNA levels, USP48 was found to be a direct transcriptional target of GLI1 in glioblastoma cells, and iASPP to be induced by GLI1/2 activation via E2F1 in melanoma cells." (PMID 35251038, 2022). "In turn, PI3K/Akt regulate the activation of GLI1 in melanoma and other cancer cells." (PMID 35752861, 2022). "Considering that ornidazole also significantly decreased both mRNA and protein expression level of Gli1 (P < 0.001), we believe that apoptosis induced by ornidazole in the melanoma tumor tissue might be partly mediated by Gli1/Bcl2/Bax-axis." (PMID 36325671, 2022). "However, we found out that silencing SMO and GLI1 resulted in decreased migration and invasiveness in melanoma under hypoxia." (PMID 36230699, 2022). "Patient-derived SSM2c melanoma cells were transfected with the reporter along with SOX2 or GLI1." (PMID 33958721, 2021). "Furthermore, inhibition of the Shh/GLI1 pathway directly, or in combination with the Ras/Akt pathway, decreases melanoma growth." (PMID 34616669, 2021). "In addition, oncogenic markers typical of basal cell carcinoma (Gli-1, Gli-2, Ptch-1, n = 2 cases) and melanoma (c-kit, MAGE, CDK4, n = 1) were markedly upregulated in skin lesions." (PMID 33509032, 2021). "Indeed, GLI2 was found to play a major role in suppressing MITF expression in human melanoma specimens, and the expression of GLI1/2 was correlated with EGFR/AXL signatures." (PMID 34572373, 2021). "Additionally, our results show that GLI1 positively regulates the expression of ERK5 in melanoma cells." (PMID 34681917, 2021). "Thereafter, we attempted to investigate the precise function of circ-GLI1 in melanoma." (PMID 32732916, 2020). "Besides, the promoting effect of circ-GLI1 on melanoma metastasis was identified here for the first time." (PMID 32732916, 2020). "Once established, this invasive melanoma signature is then stabilised via GLI1 and ZEB1 signalling." (PMID 32796736, 2020).
melanoma (continued). "To verify whether circ-GLI1 exerted functions in melanoma in a Cyr61-dependent manner, we conducted rescue assays in circ-GLI1-silenced A375 cells." (PMID 32732916, 2020). "This study focused on the role of circ-GLI1 in melanoma metastasis and its correlation with Cyr61." (PMID 32732916, 2020). "Furthermore, ectopic expression of ST3GAL1 rescues the effect of SOX2 and/or GLI1 depletion on melanoma cell invasiveness." (PMID 33203881, 2020). "Circ-GLI1 was silenced in melanoma cells by sh/circ-GLI1#1 and sh/circ-GLI1#2." (PMID 32732916, 2020). "Furthermore, we testified that overexpression of p70S6K2 reversed the suppression of circ-GLI1 silence on the protein levels of GLI1 and β-catenin in melanoma cells." (PMID 32732916, 2020). "Furtherly, we wondered how circ-GLI1 modulated Cyr61 expression in melanoma." (PMID 32732916, 2020). "Therefore, ZEB2 protein levels should be evaluated to furthermore confirm the proposed ZEB2-independent functioning of GLI1 in melanoma invasion." (PMID 32796736, 2020). "Here, we screened out a novel circRNA named has_circ_0027247 (circ-GLI1) in melanoma." (PMID 32732916, 2020). "In addition, AKT stimulates GLI1 transcriptional activity and nuclear translocation in human melanoma, prostate cancer and glioma cells, contributing to disease progression." (PMID 31244888, 2019). "Also, oncogenic NRAS and HRAS increase GLI1 function in melanoma cells, and HH-GLI signaling is required for NRAS-induced mouse melanoma growth." (PMID 30158435, 2018). "Human melanoma cell lines LOX IMVI and UACC 257 harboring BRAFV600E mutation were treated with PLX-4032 and subsequently subjected to WB analysis for the expression of GLI1 and phospho-ERK 1/2 (as a marker for MAPK inhibition)." (PMID 23935925, 2013). "In our study the expression of the SHH-GLI signaling pathway target GLI1 could be detected in 18 human melanoma cell lines and normal human melanocytes at mRNA level demonstrating the activity of this signaling pathway in human melanoma cell lines in vitro." (PMID 23935925, 2013). "Notably, the efficacy of this combinatorial treatment in melanoma cells is not influenced by BRAF, NRAS or NF1 mutational status, opening the possibility of using these compounds to treat melanoma expressing high levels of SOX2 and GLI1 irrespectively to their mutational status." (PMID 33958721, 2021). "In addition, the subgroup of melanoma cases with high expression of both SOX2 and GLI1 exhibited lower frequency of KRAS mutations (0.0182 vs. 0.292) and higher frequency of PTEN mutations (0.1272 vs. 0.0414), although the relevance of this finding needs further investigation." (PMID 33958721, 2021). "Importantly, inhibition of GLI1/2 could not only restore sensitivity to vemurafenib but also delay the onset of vemurafenib resistance and induce senescence in melanoma cells." (PMID 34572373, 2021). "Hence, we supposed that circ-GLI1 indirectly modulated Cyr61 transcription in melanoma cells." (PMID 32732916, 2020). "Furthermore, it was proven that activation of Wnt/β-catenin pathway could increase the levels of p-GSK3β (Ser9), MYC and Cyr61, while MYC overexpression elevated the levels of MYC and Cyr61 in melanoma cells with circ-GLI1 silence." (PMID 32732916, 2020). "Indeed, ST3GAL1 appears to mediate the effects of SOX2 and GLI1 on melanoma cell invasion." (PMID 33203881, 2020). "However, it is unknown whether c-Myc and HH pathway factors Gli-1 and 2 also follow the same pattern of expression in different stages of melanoma." (PMID 31820036, 2020). "Besides, silencing circ-GLI1 hindered melanoma cell metastasis as well." (PMID 32732916, 2020). "Hence, we suspected that circ-GLI1 (hsa_circ_0027247) might play a role in melanoma through regulating Cyr61." (PMID 32732916, 2020). "Next, we asked whether ST3GAL1 could mediate SOX2- and GLI1-induced melanoma invasiveness." (PMID 33203881, 2020).
melanoma (continued). "Interestingly, other members of the O-glycan biosynthesis pathway appear to be regulated by both SOX2 and GLI1, suggesting that these two TFs may promote melanoma progression through the induction of aberrant glycosylation." (PMID 33203881, 2020). "Therefore, we detected the distribution of circ-GLI1 in melanoma cells." (PMID 32732916, 2020). "Finally, we tested whether circ-GLI1 regulated Cyr61 to influence melanoma metastasis and angiogenesis in vivo." (PMID 32732916, 2020). "Furthermore, the oncogenic WIP1 phosphatase enhances GLI1 activity and stability in melanoma cells." (PMID 30558232, 2018). "In melanoma cells, ERK5 silencing reduces GLI1 and GLI2 mRNA and protein levels and inhibits GLI transcriptional activity." (PMID 39998753, 2025). "In melanoma, HH/GLI regulation involves interactions with the RAS-RAF-MEK-ERK signaling axis, thereby promoting SMO-independent GLI1 activity." (PMID 39962447, 2025). "All together, these results indicate that the MEK5/ERK5 pathway positively modulates GLI1 and GLI2 transcription factors both at transcriptional and protein levels in melanoma cells." (PMID 39998753, 2025). "As GLI1-expressing melanomas display a significant increase of PMN-MDSCs in vivo, we further investigated how GLI1 influences their behavior." (PMID 39090759, 2024). "It has been shown that the HH-GLI pathway is required for the normal proliferation of human melanocytes in vitro and that GLI1 and PTCH1 are upregulated in skin metastases compared to primary melanomas." (PMID 38892279, 2024). "Overall, this study demonstrates the role of GLI1 in promoting an immunosuppressive TME, which allows melanoma cells to evade the immune system." (PMID 39090759, 2024). "Therefore, we decided to test these Hh inhibitors in vitro in order to target SMO and/or GLI1 and analyse melanoma migration and invasion to see if they could reduce this activity as a first step in developing new therapeutical strategies for melanoma treatment." (PMID 38399442, 2024). "Our findings highlight the relevance of tumor-derived GLI1 in promoting an immune-suppressive TME, which allows melanoma cells to evade the immune system, and pave the way for the design of new combination treatments targeting GLI1." (PMID 39090759, 2024). "In the present study, we examined the effects of the Gli1 and Gli2 dual inhibitor, GANT61, in a melanoma bone destruction mouse model and investigated its tumor suppressive mechanism." (PMID 37240209, 2023). "By using a genetic approach based on the transient silencing (siRNA) of SMO, GLI1, and CAXII, we showed that melanoma cell migration and invasion were affected by CAXII and the Hh pathway." (PMID 36230699, 2022). "We demonstrated that the inhibition of both SMO and GLI1 decreased CAXII expression and impaired melanoma cell migration and invasion." (PMID 36230699, 2022). "ChIP sequencing was used to identify GLI1, GLI2, and GLI3 binding regions in human melanoma cell lines and to further confirm RNA-seq results." (PMID 36139698, 2022). "We applied RNA sequencing and combined it with ChIP sequencing to identify direct but also unique and overlapping targets of GLI1, GLI2, and GLI3 in three melanoma cell lines." (PMID 36139698, 2022). "In an effort to determine the clinical relevance of the findings above in vivo, the relationship between GLI1/2, MITF, and EGFR was determined in the TCGA melanoma cohort." (PMID 34572373, 2021). "A recent study showed that in melanoma cells the oncogenic TFs SOX2 and GLI1 co-regulate ST3GAL1 transcription." (PMID 33921986, 2021). "In further support of a positive regulation of MAPK7 by GLI1 transcription factor, GLI1 silencing resulted in the reduction of MAPK7 mRNA in all three melanoma cell lines tested." (PMID 34681917, 2021). "Consistently, we find a positive correlation between the expression of GLI1 and SOX2 in human melanoma samples and cell lines." (PMID 33958721, 2021).
melanoma (continued). "Taken together, TGF-β1/SMAD3 activates GLI1/2 via an SMO-independent mechanism to promote chemoresistance, enhance invasive potential, and promote the proliferation of melanoma." (PMID 34572373, 2021). "To gain further insight into the neoplastic potential of skin nevi, we evaluated the expression of oncogenic markers characteristic of BCC (Ptch-1, Gli-1, and Gli-2), SCC (K8, K17, and p63), and melanoma (c-kit, MAGE, and CDK4)." (PMID 33509032, 2021). "Using a 3D reconstructed human melanoma skin model, both untreated naïve and resistant melanoma cells had elevated levels of MMP2/9 and were highly invasive, but treatment with GANT61, which downregulated GLI1/2 expression, reversed these effects." (PMID 34572373, 2021). "The western blot also elucidated that ST3GAL1, SOX2, GLI1, and AXL all have higher expression in metastatic melanomas as compared to primary melanomas." (PMID 35008286, 2021). "Therefore, we also evaluated whether circ-GLI1 affected GLI1 expression in melanoma." (PMID 32732916, 2020). "Hence, we suspected that circ-GLI1 might function in melanoma by influencing GLI1 expression." (PMID 32732916, 2020). "Here we show that the sialyltransferase ST3GAL1 is transcriptionally regulated by both GLI1 and SOX2 in melanoma and is a crucial driver of melanoma cell invasiveness and melanoma metastasis in vivo." (PMID 33203881, 2020). "Our results showed that both GLI1 and SOX2 increased melanoma cell invasion and that depletion of ST3GAL1 was able to suppress the effects of both SOX2 and GLI1." (PMID 33203881, 2020). "Western blots showed that primary melanoma cells express lower levels of SOX2, GLI1, ST3GAL1, and AXL than metastatic melanoma cells, and that the latters harbor a stronger activation of SOX2/GLI1-ST3GAL1-AXL axis." (PMID 33203881, 2020). "Overall, these data reveal ST3GAL1 as a key downstream mediator that contributes to the aggressive behavior of melanoma cells induced by SOX2 and GLI1." (PMID 33203881, 2020). "Since GLI1-mediated regulation of SOX2 regulates the self-renewal of lung and melanoma CSCs, we examined SOX2 levels using ciclesonide." (PMID 32033067, 2020). "In human melanoma cells, oncogenic NRAS (NRASQ61K) and HRAS (HRASV 12G) are able to enhance transcriptional activity and nuclear localization of GLI1." (PMID 31244888, 2019). "For instance, in melanoma cells oncogenic NRAS (NRASQ61K) and HRAS (HRASV12G) have been shown to activate GLI1 function, enhancing its transcriptional activity and nuclear localization." (PMID 30934935, 2019). "SOX2is regulated by HH signaling where transcriptionfactorsGLI1 and GLI2 directly bind to the proximal promoter region of SOX2 in primary melanoma cells.Also, human SOX14 expression is GLI1 dependent in U87MG cells and SHH dependent in U87MG and HepG2 cells." (PMID 26588701, 2015). "In melanoma cells, oncogenic Ras activity, dominant active MEK1 and dominant active AKT1 all increased the subcellular nuclear localization of exogenous Gli1." (PMID 26512695, 2015). "Two studies also described high levels of GLI1 and GLI2 transcription factor mRNA in human metastatic melanoma tissue as compared to primary melanoma tissue." (PMID 24287465, 2013). "Expression of Shh targets including the Gli1 transcription factor and osteopontin (OPN) increases gradually in melanoma cells of increasing metastatic potential." (PMID 24281103, 2010). "Gli1 silencing led to decreased OPN expression and decreased proliferation, invasion, and migration of melanoma cells in vitro and inhibition of growth and metastasis in vivo." (PMID 24281103, 2010). "Furthermore, the SOX-BRD4 transcriptional complex induces the expression of GLI1 and GLI2 in human melanoma cells." (PMID 39962447, 2025). "Besides p300, in melanoma, SOX2 forms a complex with GLI1 and cooperatively transactivates ST3GAL1, which promotes melanoma metastasis via upregulating AXL." (PMID 38331879, 2024).